PPARG (peroxisome proliferator activated receptor gamma)
Diseases named in the same sentence as PPARG in open-access papers (continued):
Sharing a sentence is not in itself a finding about the gene and the disease.
osteoporosis (continued). "Peroxisome proliferator-activated receptor-γ (PPARγ) is a critical regulator of adipogenesis and bone metabolism, playing complex roles in osteoporosis." (PMID 39707534, 2024). "In this study, taurine demonstrated significant potential for osteoporosis management by modulating key genetic pathways, particularly through the inhibition of PPARγ." (PMID 39707534, 2024). "It is one of the potential effective ways to treat osteoporosis by regulating the PPARγ signaling pathway and bone metabolism." (PMID 39684847, 2024). "Given these considerations, the purpose of this study was to examine the likely molecular mechanism/s by which taurine and homocysteine interact with PPARγ in relation to osteoporosis." (PMID 39707534, 2024). "Given the conflicting reports regarding homocysteine’s influence on PPARγ, we sought to clarify its effects on osteoporosis in this study, while also examining the contrasting effects of taurine." (PMID 39707534, 2024). "This study aimed to examine the relationship between PPARγ and PPARGC1A polymorphisms and the BRONJ development in female osteoporosis patients undergoing bisphosphonate treatment." (PMID 37513946, 2023). "Single-cell mRNA sequencing analysis show that PPARγ is highly expressed in the bone tissue of osteoporosis patients, which highlights the role of PPARγ in osteoporosis." (PMID 36951483, 2023). "FTO was upregulated in the process of aging and osteoporosis in mice, which promoted the shift of BMSCs to adipocytes rather than osteoblasts and inhibits bone formation through demethylating the mRNA of PPARγ." (PMID 38020896, 2023). "To confirm that PPARγ is the specific effector molecule of osteoporosis, we analysed the expression level of PPARγ in human bone tissue using published single-cell mRNA sequencing datasets." (PMID 36951483, 2023). "Our study objective was to examine the relationship between PPARγ and PPARGC1A polymorphisms and the development of BRONJ in patients with osteoporosis patients undergoing bisphosphonate treatment." (PMID 37513946, 2023). "The results showed that the PPARγ protein levels in osteoporosis patients were significantly higher than those in healthy controls." (PMID 36951483, 2023). "In this study, we demonstrated that metformin enhanced osteoblast differentiation and downregulated the protein level of PPARγ in an osteoporosis cell model." (PMID 36951483, 2023). "In this study, our objective was to investigate the association between PPARγ and PPARGC1A polymorphisms and the development of BRONJ in osteoporosis patients undergoing bisphosphonate treatment." (PMID 37513946, 2023). "This is possibly due to long-term PPARγ-driven side effects such as peripheral edema, weight gain, and osteoporosis." (PMID 36613602, 2022). "It has been shown that during aging, the expression level of PPARγ increases, which leads to increased binding of MSCs to adipocytes, so the role of PPARγ in the development of osteoporosis with aging is the subject of study." (PMID 35892126, 2022). "Due to strong but unspecific activation of PPARγ-directed gene expression in various tissues the thiazolidinediones induced liver diseases, weight gain, oedema, heart failure, osteoporosis, and cancer." (PMID 24265809, 2013). "This evidence coupled with the fact that bone marrow fat increases and bone marrow osteoblasts decrease with age in both animals and humans demonstrates a possible strong link between PPARγ and osteoporosis." (PMID 22518296, 2012). "By leading to the differentiation of adipocytes over osteoblasts, activation of PPARγ subsequently leads to a decrease in bone mineral density and appears to be strongly correlated to the development and progression of osteoporosis." (PMID 22518296, 2012). "The balance between bone and adipocyte generation in bone marrow is affected by factors including aging, osteoporosis, and activation of PPARγ." (PMID 21103061, 2010).
osteoporosis (continued). "Addressing these questions will advance ourability to prevent TZD-induced osteoporosis and will provide a betterunderstanding of the role of PPARγ activation in bone metabolism." (PMID 18795105, 2008). "Therefore, there is an urgent need for novel approaches to activate PPARγ while avoiding weight gain, fluid retention, and osteoporosis." (PMID 40119175, 2025). "ZGP improved ovariectomy‐induced osteoporosis by reducing PPARG levels." (PMID 40417738, 2025). "PPARG, as a transcription factor regulating sclerostin production, may become a therapeutic target in osteoporosis therapy." (PMID 39062013, 2024). "Collectively, these findings suggest that LYC attenuates osteoporotic bone loss through promoting osteogenesis and inhibiting adipogenesis via regulation of the FoxO1/PPARγ pathway driven by oxidative stress, presenting a novel strategy for osteoporosis management." (PMID 38794681, 2024). "In addition, inhibition of PPARγ transcriptional activity in MSCs to enhance osteogenesis and inhibit lipogenesis is also an effective means to alleviate osteoporosis." (PMID 38523674, 2024). "In contrast, an increased expression of PPARγ triggered by oxidative stress may divert BMSCs from osteogenesis to adipogenesis, thus contributing to the development of osteoporosis." (PMID 38794681, 2024). "However since both the compounds showed inhibition towards PPARγ, it was essential to conduct in-vitro tests to elucidate their mechanisms of action concerning osteoporosis." (PMID 39707534, 2024). "We conclude that: (i) PPARγ is the effector through which metformin prevents osteoporosis." (PMID 36951483, 2023). "Pparγ, a critical regulator of adipogenesis, was also identified as a biomarker for osteoporosis." (PMID 38020896, 2023). "During bone resorption, AB-EVs secreted by osteocytes are released from the bone matrix into bone marrow, where AB-EVs deliver miR-483-5p to promote the expression of PPARγ and the differentiation of BMSCs into adipocytes rather than osteoblasts, thus leading to bone-fat imbalance and osteoporosis." (PMID 35304471, 2022). "Moreover, drugs used in the treatment of T2D, specifically PPARγ agonists, have also been reported to affect bone cell function and result in reduced BMD and increased risk of osteoporosis and fractures." (PMID 33990655, 2021). "Angelicin also prevented osteoporosis by downregulating the PPARγ protein." (PMID 31781261, 2019). "In support of this notion, it has been shown that alendronate, a drug used to treat osteoporosis in postmenopausal women, can delay adipogenesis and enhance osteogenesis by reducing the expression of PPARγ, the adipogenic transcription factor, in human mesenchymal stem cells." (PMID 27110299, 2016). "Third, PPARG increases osteoporosis while TR4 decreases osteoporosis." (PMID 25859557, 2015). "Peroxisome proliferator-activated receptor gamma (PPARγ), known as the master regulator of adipogenesis, has been regarded as a promising target for new anti-osteoporosis therapy due to its role in regulating bone marrow mesenchymal stem/progenitor cell (BMSC) lineage commitment." (PMID 25666993, 2015). "The signalling cascades related to PPARγ are potential therapeutic targets to promote osteoblast differentiation in osteoporosis and age-related osteopenia and therapeutic methods that act through suppression of PPARγ or inhibition of its ligand synthesis have been proposed." (PMID 23937351, 2013). "Moreover, compared with RSG, NJT‐2 does not exhibit the side effects associated with traditional PPARγ complete agonists, particularly in terms of cardiovascular toxicity and osteoporosis." (PMID 38988496, 2024). "Even though a lot is known about the way agonists interact with PPARγ to elicit its role in various processes—predominantly adipogenesis, PPARγ antagonism is just starting to be understood in relation to its role in bone biology and especially in chronic bone diseases like osteoporosis." (PMID 39707534, 2024).
osteoporosis (continued). "In addition, the interaction of PPARγ with specific promoter elements in hematopoietic stem cells promotes osteoclastogenesis, highlighting the complex interplay between factors that drive the progression of osteoporosis." (PMID 39049966, 2024). "Furthermore, we find that PPARγ is the effector through which metformin prevents osteoporosis." (PMID 36951483, 2023). "However, long-term activation of PPARγ can lead to weight gain, fluid retention, and osteoporosis." (PMID 30729133, 2019). "Network pharmacology identified key osteoporosis-related targets involved in inflammatory signaling, hormone regulation, and bone remodeling, with key hubs including IL-6, STAT3, NF-κB, and PPARγ." (PMID 41562931, 2026). "Thus, targeting PPARγ may be a promising approach to prevent osteoporosis." (PMID 36951483, 2023). "Our research established a link between osteoporosis and RNA-binding proteins, and we discovered a regulatory relationship between MSI2 and PPARγ signaling." (PMID 35301280, 2022). "In summary, SMFs protected against ATRA- or Dex-induced osteoporosis in mice by promoting the RUNX2-mediated osteogenic differentiation and suppressing the PPARγ-mediated lipogenic differentiation of BMSCs." (PMID 33198804, 2020). "In this study, we found that the expression of miR-10b was positively correlated with bone formation marker genes ALP, RUNX2 and OPN, and negatively correlated with adipogenic markers CEBPα, PPARγ and AP2 in clinical osteoporosis samples." (PMID 30574418, 2018). "More provocatively, because PPARγ acts as a double-edged sword to not only inhibit bone formation but also promote bone resorption, bone-specific PPARγ antagonists may represent a potential new therapeutic strategy for the simultaneous anabolic and anticatabolic treatment of osteoporosis." (PMID 22135675, 2011). "In the present study, molecular docking analysis revealed that asiatic acid exhibited stronger binding affinities toward several osteoporosis-related proteins, including STAT3, PPARγ, NF-κB p105, COX-2, ESRα, TLR4, and NF-κB p65, compared to their native ligands." (PMID 41562931, 2026). "Additionally, PPARG, PTGS2, IL6, STAT3, and JUN have been reported to play important roles in the development of osteoporosis." (PMID 40299567, 2025). "In addition, we analysed the PPARγ protein levels in the bone tissue of 30 T2DM patients, including 20 osteoporosis patients and 10 healthy individuals." (PMID 36951483, 2023). "Because of these multiple faces of PPARG, inhibition of this nuclear hormone receptor does not seem an attractive approach for the prevention of fatty bone marrow formation in osteoporosis patients." (PMID 27562730, 2016). "Extensive research demonstrates that PPARγ plays a pivotal role in regulating MSC specification towards adipogenesis versus osteogenesis and is instrumental in governing both bone mineral density and osteoporosis." (PMID 22518296, 2012). "In our study, JGSQP activated the expression of p-AKT along with multiple bone formation and adipogenesis-related genes (Wnt10b, Osx, BMP2, PPARγ, Fabp4, and Fndc5), suggesting that it may ameliorate murine OVX-induced osteoporosis with KYD by controlling the bone-fat balance via the AKT pathway." (PMID 32963560, 2020). "We collected 30 clinical samples from osteoporosis patients of different ages and analyzed the correlation between the expression of miR-10b and the bone formation marker genes ALP, OPN and RUNX2, and the correlation between miR-10b and adipocyte formation markers CEBPα, PPARγ and AP2." (PMID 30574418, 2018).
Parkinson disease (71 papers, 2008 to 2026). A progressive degenerative disorder of the central nervous system characterized by loss of dopamine producing neurons in the substantia nigra and the presence of Lewy bodies in the substantia nigra and locus coeruleus. "PPARγ agonists such as pioglitazone and rosiglitazone have also been confirmed to exert neuroprotective effects in a range of Parkinson’s disease animal models, significantly improving motor and cognitive impairments in mouse." (PMID 39050892, 2024). "PGC-1 and PPARγ have been studied as therapeutic targets in Parkinson's disease and have been shown to confer neuroprotective effects in dopamine neurons." (PMID 35250674, 2022). "Studies have already demonstrated the ability of CBD to modulate the immune response by acting an agonist of PPARγ and altering NF‐κB signalling, which is up‐regulated in both microglia and astrocytes of Parkinson's disease patients." (PMID 32608035, 2020). "For this reason, while evaluating its possible dual role, tideglusib was compared with pioglitazone, a well-known PPARγ agonist, which was previously shown to be effective in Parkinson’s disease models." (PMID 30965670, 2019). "In a model of Parkinson’s disease (PD), Nurr1 agonists affect mitochondrial membrane potential stabilization and intracellular ROS production in a manner dependent on PPARγ." (PMID 33817160, 2019). "It has been shown in a MPP+/MPTP model of Parkinson's disease that PPARγ activity was important for protecting against MPTP toxicity." (PMID 30410641, 2018). "Activation of peroxisome proliferator-activated receptors (PPARs), namely PPARγ and PPARδ, has been shown to provide neuroprotection in a number of neurodegenerative disorders, such as Alzheimer’s and Parkinson’s disease (PD)." (PMID 26028469, 2015). "Previous studies have shown beneficial effects of PPARγ activation in several animal models of neurological disease, including cerebral ischemia, multiple sclerosis, Parkinson’s disease, and AD." (PMID 24838579, 2015). "Activation of the peroxisome proliferator-activated receptor gamma (PPAR-γ) has been proposed as a possible neuroprotective strategy to slow down the progression of early Parkinson's disease (PD)." (PMID 21819568, 2011). "PPARγ agonists have been considered for the treatment of Alzheimer’s and Parkinson’s disease." (PMID 36768419, 2023). "Preclinical trials with different PPARγ agonists in several animal models of Parkinson’s disease." (PMID 36834679, 2023). "Moreover, other results also showed that PPARγ was a critical therapeutic target in Parkinson’s disease, by regulating fatty acid oxidation, immune responses and the mitochondrial function." (PMID 32536974, 2020). "Additionally, the neuroprotective properties of CBD in Alzheimer’s and Parkinson’s diseases are also mediated by the interaction with PPARγ." (PMID 33171772, 2020). "Similarly, PPARγ activation can restore neurogenesis in the OH-DA model of Parkinson’s disease and prevent amyloid-beta-induced cell death of human neural stem cells." (PMID 30899454, 2019). "The agonist of PPARγ has been extensively investigated for its anti-inflammatory and neuroprotection in brain ischemia, spinal injury and other CNS injuries, experimental autoimmune encephalomyelitis, Parkinson's disease, and other neurodegenerative diseases." (PMID 26844229, 2015). "The development of more specific ligands of PPARγ, namely the thiazolidinedione (TZD) class of oral antidiabetics has prompted experimental studies to further validate PPARγ-mediated neuroprotection in models of cerebral ischemia, Parkinson’s disease (PD), amyotrophic lateral sclerosis, and AD." (PMID 24838579, 2015). "Similarly, antioxidative, neuroprotective function for PPARγ was reported in a model of Parkinson's disease." (PMID 24874187, 2014). "► We investigate the role of PPARγ in a model of Parkinson's disease." (PMID 22417924, 2012).
Parkinson disease (continued). "Such protective effects have been observed with PPARγ agonist use in models of ischemic and hemorrhagic stroke, and in models of CNS disease including Alzheimer's disease, multiple sclerosis (MS), amyotrophic lateral sclerosis, and Parkinson's disease." (PMID 21772838, 2012). "Proliferator-activated receptor γ (PPARγ) activation can result in transcription of proteins involved in oxidative stress defence and mitochondrial biogenesis which could rescue mitochondrial dysfunction in Parkinson's disease (PD)." (PMID 27366949, 2016). "PPARγ agonists have also been tested in neuronal cells treated with acetaldehyde, a toxin that mimics Parkinson disease (PD) neurodegeneration." (PMID 25246934, 2014). "Peroxisome proliferator-activated receptor gamma (PPARγ), due to its widespread distribution in various brain regions and anti-inflammatory properties, may be a potential target for conferring neuroprotection in neurodegenerative diseases such as Alzheimer's and Parkinson's diseases." (PMID 40821125, 2025). "Data have also been accruing on the neuroprotective properties of PPARγ agonists in models of CNS injury, ischemic stroke, and diseases of the CNS including multiple sclerosis, ALS, and Parkinson's disease." (PMID 21772838, 2012). "This study explored the impact of the PPARγ agonist rosiglitazone and the PPARγ antagonist GW9662 in the MPP+/MPTP (1-methyl-4-phenylpyridinium/1-methyl-4-phenyl-1,2,3,6-tetrahydropyridine) model of Parkinson's disease, focussing on oxidative stress mechanisms." (PMID 22417924, 2012).